PRR14L (proline rich 14 like)
Synonyms: C22orf30; MGC50372
Tractability: PROTAC: ubiquitination databases record sites on it.
Gene: Protein-coding gene on chromosome 22 (31,676,256 to 31,750,207, reverse strand). Ensembl gene ENSG00000183530.
Subcellular location (Human Protein Atlas): Nucleoplasm
Genetic constraint (gnomAD): Loss-of-function variants: 74 observed, 140.75 expected, observed/expected ratio (o/e) 0.53, 90% interval 0.44 to 0.64. The upper end of that interval is the gene's LOEUF score, 0.64, which puts it in group 2 of 6, group 1 being the genes least tolerant of losing a copy. Missense variants: 2,427 observed, 2,633 expected, observed/expected ratio (o/e) 0.92, 90% interval 0.89 to 0.95. Synonymous variants: 872 observed, 949.24 expected, observed/expected ratio (o/e) 0.92, 90% interval 0.87 to 0.97.
Homologues: Orthologues: chimpanzee PRR14L (99% identical), macaque PRR14L (93% identical), dog PRR14L (71% identical), rabbit PRR14L (66% identical), guinea pig PRR14L (66% identical), pig PRR14L (58% identical), rat Prr14l (54% identical), mouse Prr14l (54% identical), tropical clawed frog prr14l (17% identical). Paralogues in human: PRR14 (6% identical).
Diseases named in the same sentence as PRR14L in open-access papers:
PRR14L is named in the same sentence as 7 diseases in open-access papers, as found by Europe PMC text mining. Sharing a sentence is not in itself a finding about the gene and the disease. The quoted sentences say what the papers report.
chronic myelomonocytic leukemia (2 papers, 2023 to 2025). A myelodysplastic/myeloproliferative neoplasm which is characterized by persistent monocytosis, absence of a Philadelphia chromosome and BCR/ABL fusion gene, fewer than 20 percent blasts in the bone marrow and blood, myelodysplasia, and absence of PDGFRA or PDGFRB rearrangement. "Our screen identified PRR14L, a poorly understood nuclear gene that was previously shown to harbor mutations causing clonality in chronic myelomonocytic leukemia (CMML)." (PMID 41279925, 2025). "In this study, we identified a number of genes known to regulate aneuploidy and mitosis, and subsequently focused on PRR14L, a ubiquitously expressed gene previously implicated in chronic myelomonocytic leukemia (CMML)." (PMID 41279925, 2025).
colorectal cancer (1 paper, 2017). A primary or metastatic malignant neoplasm that affects the colon or rectum. "For instance, a model of seven-gene signatures (NHLRC3, ZDHHC21, PRR14L, CCBL1, PTPRB, PNPO and PPIP5K2) was applied to predict OS by dividing colorectal cancer (CRC) patients into low-risk and high-risk groups." (PMID 28827775, 2017).
cancer (1 paper, 2025). A tumor composed of atypical neoplastic, often pleomorphic cells that invade other tissues. "A model derived from our findings provides a rationale for exploiting MPS1 inhibition as a potential vulnerability in cancers containing either PRR14L loss of function mutations or FGFR-TACC3 fusions." (PMID 41279925, 2025).
PRR14L also shares sentences with these, for which no sentence is quoted: adenosarcoma (1 paper); asthma (1); leukaemia (1); uterine sarcomas (1).